PDCD4 (programmed cell death 4)
Diseases named in the same sentence as PDCD4 in open-access papers (continued):
Sharing a sentence is not in itself a finding about the gene and the disease.
sarcoma (1 paper, 2023). A usually aggressive malignant neoplasm of the soft tissue or bone. "JNK/p38-MAPK, PVT1/ERG, programmed cell death 4 (PDCD4)/ERK1/2, SOCS3/JAK2/STAT3, TGF-β/COL6A1, IL6/STAT3, PI3K/Akt/mTOR, and Hedgehog in exosomes regulate genes or signaling pathways to promote the migration and metastasis of sarcoma cells." (PMID 36979391, 2023).
skin squamous cell carcinoma (1 paper, 2014). A carcinoma arising from the squamous cells of the epidermis. "However, the expression of miR-21 and its target genes, PDCD4 and PTEN, has not yet been reported in skin squamous cell carcinoma (SCC)." (PMID 24959246, 2014).
squamous cell tumor (1 paper, 2016). "Like with CSL, we have found that silencing of PDCD4 was sufficient to induced fibroblast senescence and SMS production and, importantly, enhance squamous cell tumor formation." (PMID 27542230, 2016).
thyroid-associated ophthalmopathy (1 paper, 2022). "Via miRNA-21-mediated PDCD4 downregulation, PDGF-BB stimulates cell proliferation and promotes the development of thyroid-associated ophthalmopathy." (PMID 35847662, 2022).
tonsil cancer (1 paper, 2016). A primary or metastatic malignant neoplasm that affects the tonsil. "It is not known whether PDCD4 expression is a predictor of outcome in tonsil cancer." (PMID 26867589, 2016).
tonsillar cancer (1 paper, 2016). "Therefore the reduction of miR-21 levels in tonsillar cancer cell lines was marked by an increase in PDCD4 expression." (PMID 26867589, 2016).
type 2 diabetes (1 paper, 2022). "Although we have shown that miR-21 in islet β cell promotes insulin secretion though Pdcd4-AP-1-Glut2 pathway, whether exosomal miR-21 released by islet β cell regulates insulin resistance and the development of type 2 diabetes warrants further investigation." (PMID 35729232, 2022).
urinary system cancers (1 paper, 2016). "Four studies of digestive system cancers and one study of urinary system cancers examined associations between tumor size and PDCD4 expression level." (PMID 27852288, 2016). "In urinary system cancer, PDCD4 suppression was associated with the metastatic status of the patients." (PMID 27852288, 2016). "In a stratified analysis, reduced PDCD4 expression level was associated with late T subcategories in head and neck tumors and urinary system cancers as well as distant metastasis of urinary system cancers." (PMID 27852288, 2016). "Because low PDCD4 expression was significantly associated with metastasis in urinary system cancers, PDCD4 could be a novel target for improving the prognosis of this malignancy." (PMID 27852288, 2016). "Down-regulation of PDCD4 was significantly associated with short overall survival of patients with head and neck (HR: 3.44, 95% CI 2.38–4.98), breast (HR: 1.86, 95% CI 1.36–2.54), digestive system (HR: 2.12, 95% CI 1.75–2.56), and urinary system cancers (HR: 3.16, 95% CI 1.06–9.41)." (PMID 27852288, 2016).
tumor (636 papers, 2006 to 2026). "miR-21 exerts its oncogenic effects by repressing the tumor suppressor gene PDCD4, whose low expression in tumor tissues is in turn associated with worse clinical outcomes." (PMID 41596525, 2026). "IHC demonstrated a progressive loss of PDCD4 expression with decreasing tumor differentiation, consistent with its significant downregulation in ATC tissues based on GEO datasets." (PMID 40908584, 2025). "We conducted a thorough pan-cancer research to examine PDCD4 expression patterns, mutational features, prognostic importance, and its possible function in tumor immune regulation because cancer is known to increase the incidence of AF." (PMID 40766329, 2025). "Collectively, these findings suggest that PDCD4 loss reprograms the tumor secretome and promotes an immunosuppressive microenvironment through eIF4A ‐dependent translational activation." (PMID 40908584, 2025). "Previous studies have demonstrated that PDCD4 downregulation is associated with tumor progression, metastasis, and poor prognosis in various malignancies, including colorectal, lung, and breast cancers." (PMID 41614853, 2025). "Low PDCD4 signature scores were associated with significantly worse overall survival (HR = 2.17, 95% CI: 1.58–2.98, p < 0.001) and advanced tumor stage." (PMID 41614853, 2025). "PDCD4 has been implicated in several of these mechanisms, including its regulation by miRNAs and ubiquitin-mediated degradation, which affects its tumor suppressive activity across multiple cancers." (PMID 40766329, 2025). "PDCD4 expression has been reported to be downregulated in many tumor tissues and a loss of expression correlates with tumor development and progression." (PMID 41439995, 2025). "Although the loss of PDCD4 expression has been associated with tumorigenesis and tumor progression in solid tumors." (PMID 41234771, 2025). "The signature’s strong associations with both advanced stage (OR = 3.27) and high grade (OR = 3.16) suggest that PDCD4-related molecular alterations contribute to the biological processes underlying tumor invasion, metastasis, and dedifferentiation." (PMID 41614853, 2025). "Among these apoptotic genes, PDCD4, a critical tumor suppressor gene that encodes a pro-apoptotic protein, which stimulates apoptosis via the inhibition of procaspase-3 mRNA translation, was identified to be upregulated by SND1 silencing at the gene level." (PMID 39885142, 2025). "Ctla4 induces Pdcd4 in cytotoxic T cells, and Pdcd4 deficiency enhances their anti-tumor effector functions." (PMID 38645169, 2024). "Initially identified in a mouse epidermal cell system, the PDCD4 gene encodes a 64 kDa protein that is more abundant in tumor promoter-resistant cells compared to tumor promoter-sensitive cells undergoing transformation." (PMID 39114567, 2024). "Studies have linked the loss of PDCD4 expression to tumor progression in various cancers such as lung, colon, prostate, and breast." (PMID 39114567, 2024). "PDCD4, the other gene region that was identified in the AA stratum, is a tumor suppressor gene that encodes a protein that binds to eukaryotic translation initiation factor 4A1." (PMID 38162683, 2023). "PDCD4 expression is therefore generally associated with tumorigenesis, tumour progression and metastasis." (PMID 35847932, 2022). "Although PDCD4 is a tumour suppressor, it is associated with a pro-inflammatory state, whereas the oncomir miRNA-21, an inhibitor of PDCD4 expression, is thought to be anti-inflammatory." (PMID 35847932, 2022). "Our results demonstrated that Dox-induced chemoresistance was linked to the downregulation of PDCD4 in variant B cells, which promotes the invasion and metastasis of tumor cells." (PMID 36552834, 2022). "Snail-overexpressing HNSCC cells can, by secretion of miR-21-rich exosomes, promote M2-like polarization of tumor-associated macrophages by miR-21-mediated suppression of transcription of target genes such as programmed cell death protein 4 (PDCD4) and IL12A." (PMID 35267467, 2022).
tumor (continued). "PDCD4 acts as a tumor suppressor as its expression is frequently downregulated in cancers compared to normal tissues and Pdcd4 deletion is associated with increased lymphomagenesis in mice." (PMID 35306137, 2022). "Tumours of the GI tract are frequently associated with inflammation, increased miRNA-21 expression and suppression of PDCD4." (PMID 35847932, 2022). "For instance, reduction in EZH2 and H3K27me3 enrichment in the promoter of programmed cell death 4 is associated with impairments in cell proliferation and tumor growth." (PMID 35414117, 2022). "Conversely, overexpression of PDCD4 cDNA in the transformation-susceptible JB6 cells endowed resistance to tumor promoter-induced transformation." (PMID 35795053, 2022). "We revealed its underlying mechanism as a tumor suppressor to activate PDCD4 via serving as a sponge of miR-330-3p." (PMID 33744861, 2021). "PRMT5 was also shown to associate with Programmed Cell Death Protein 4 (PDCD4) and reduce its tumour‐suppressor activity in MCF7 cells." (PMID 33462997, 2021). "Loss or downregulation of PDCD4 is associated with tumor progression and poor outcomes in different malignancies, such as head and neck, brain, breast, lung, digestive, reproductive, and urinary system cancers." (PMID 33801444, 2021). "We next evaluated PDCD4 expression in association with survival in the tumor and stroma of brain metastases." (PMID 33801444, 2021). "Loss of PDCD4 has been associated with tumor transformation and poor prognosis in a variety of cancers." (PMID 34359600, 2021). "We next evaluated the association between PDCD4 expression and density of tumor-infiltrating lymphocytes as measured by CD3 (for T cells) or CD20 (for B cells) positivity, and macrophages as measured by CD68 positivity." (PMID 33801444, 2021). "PDCD4 expression in the tumor microenvironment is associated with increased immune cell infiltration." (PMID 33801444, 2021). "High PDCD4 levels in surrounding tumor tissue were also associated with increased infiltrating immune cells." (PMID 33801444, 2021). "Numerous studies show that miR-21-5p promotes carcinogenesis and tumor progression by targeting genes encoding PDCD4, PTEN, BTG2, FasL, IGFBP3, TGF-β1, FBXO11, and TIMP3." (PMID 33396321, 2020). "PDCD4 is a tumor suppressor gene that has been previously implicated in the progression of many types of tumours." (PMID 32354352, 2020). "In this report, we found that the tumor suppressor PDCD4 was degraded by the p62-mediated autophagy system, showing that autophagy is at least one of the mechanism(s) underlying the PDCD4 downregulation in cancer cells." (PMID 31952347, 2020). "In this regard UFs would differ from other tumors where the loss of PDCD-4 is associated with tumor progression." (PMID 32344726, 2020). "This tumor-associated lncRNA was reported to function as an oncogene by downregulating the expression of PDCD4 through recruiting EZH2 and altering trimethylation levels of H3K27 in ESCC cells." (PMID 32194853, 2020). "PDCD4 loss or down-regulation has been correlated with tumor progression and poor prognosis in different tumors of thyroid, colon, esophagus, and ovary." (PMID 29707109, 2018). "SPE-alt-PEG/GFP has been shown to deliver the Pdcd4 gene to the lungs, causing significant reductions in tumor size and tumor number in a Kras-LA1 mouse model of lung cancer, when compared with PEI 25K alone." (PMID 28290155, 2017). "Pdcd4 has recently shown to be a novel tumour suppressor gene demonstrating down-regulation or loss of expression in several types of cancer." (PMID 28750063, 2017). "Programmed cell death 4 (PDCD4) is a tumour suppressor implicated in cancer development and progression and was recently identified as a repressor of cap-independent translation of specific genes involved in the regulation of apoptosis." (PMID 26595526, 2016).
tumor (continued). "It is also interesting to note that upregulation of certain proteins were somewhat counterintuitive, specifically TSC1, TSC2, and PDCD4 as these proteins are typically associated with tumor suppression." (PMID 25999352, 2015). "Programmed cell death 4 (PDCD4) is a tumor suppressor that has been implicated in the development of a broad spectrum of human tumors." (PMID 26703592, 2015). "In the search of CRL3IBTK substrates, we found that IBtkα in vivo associated with Pdcd4, a tumor suppressor involved in several cellular processes, including translation repression." (PMID 25882842, 2015). "miR-21 also targets the tumor suppressor genes tropomyosin 1 (TPM1), programmed cell death 4 (PDCD4), and Maspin; the latter two have been implicated in the suppression of tumor invasion and metastasis." (PMID 24490161, 2013). "PDCD4 is a putative target of miR-21 and is implicated in the metastatic potential of pancreatic tumors, and maspin is a well-known tumor suppressor that can suppress tumor growth, invasion and metastasis." (PMID 22403704, 2012). "These tumor- and metastatic-suppressive effects of resveratrol were associated with reduced miR-21 and pAkt, and elevated PDCD4 levels." (PMID 23272133, 2012). "Loss of the tumor suppressor Pdcd4 was reported for various tumor entities and proposed as a prognostic marker in tumorigenesis." (PMID 23056346, 2012). "Later investigations demonstrated that loss of PDCD4 expression was associated with tumor progression in carcinomas of the lung, colon, prostate, and breast." (PMID 19480673, 2009). "In RCC specifically, preliminary evidence suggests that PDCD4 expression may be associated with tumor grade and patient outcomes, though comprehensive prognostic studies remain limited." (PMID 41614853, 2025). "However, the mechanism underlying the tumor suppressive role of PDCD4, so far, is poorly understood." (PMID 39885142, 2025). "Moreover, deletion of the NoLS domain in the PDCD4 protein leads to the loss of its tumor-suppressive function." (PMID 41234771, 2025). "PDCD4 knockdown by antisense transfection of P- cells rendered the cells susceptible to transformation, whereas overexpression of the recombinant protein made transformation sensitive P+ cells insensitive to tumour promotion." (PMID 35847932, 2022). "Many cancers of the GI tract have suppression of the tumour suppressor Programmed Cell Death 4 (PDCD4) and this has been linked to the expression of microRNAs which bind to the untranslated region of PDCD4 mRNA and either inhibit translation or target the mRNA for degradation." (PMID 35847932, 2022). "The reduction of PDCD4 in variant B could alleviate ER stress or promote adaptations related to its tumor suppressor function." (PMID 36552834, 2022). "PDCD4 and eIF4A may become tightly associated during tumor development, and also potentially during drug resistance." (PMID 36552834, 2022). "Moreover, meta-analysis has confirmed that low PDCD4 expression is strongly associated with the differentiation status of solid tumours and with tumour size." (PMID 35847932, 2022). "Previous bioinformatics analysis has confirmed that PDCD4 contains the binding site of miR-21 and acts as a tumor suppressor in the regulation of various processes associated with the development of cancer, including cell proliferation, invasion, metastasis, and neoplastic transformation." (PMID 34885115, 2021). "Furthermore, PDCD4 downregulation in tumor cells is associated with drug resistance, whereas its expression enhances sensitivity to chemo- and radio-therapy." (PMID 33801444, 2021). "PDCD4 expression in these cells was positively correlated with genes involved in cytolysis, thus potentially supporting the role of PDCD4 in immune-directed cell lysis of tumor cells and explaining how high PDCD4 levels are associated with improved brain metastasis survival." (PMID 33801444, 2021).
tumor (continued). "Moreover, the inhibition or deficiency of PDCD4 enhances tumorigenesis and tumor progression in vivo." (PMID 33304903, 2020). "We therefore hypothesized that defective G1/S-checkpoint control, which is a hallmark of many tumor cells, might circumvent the requirement for PDCD4 to pass the G1/S-boundary." (PMID 32066800, 2020). "In addition, we showed that miR-21-mediated oncogenic properties were associated with their targeting/inhibitory function on PDCD4 (a tumor suppressor)." (PMID 31269723, 2019). "Further dissection of ncRNAs in the PDCD4 pathway at the molecular and cellular levels will provide insights into the underlying mechanisms of PDCD4 in tumor suppression and devise novel avenues in drug development against cancer and other PDCD4-associated diseases." (PMID 31620370, 2019). "Over-expression of miR-21 may induce a decrease in the levels of PDCD4, a well-known tumor suppressor molecule associated with poor outcomes in cancer patients." (PMID 29212210, 2017). "Similarly, PDCD4 overexpression attenuated the promotive effect of tumor growth caused by miR-208a-3p overexpression." (PMID 27634902, 2016). "However, technical knockout or knockdown of Pdcd4 gene probably brings the risk for tumorigenesis, for Pdcd4 has been well recognized as a tumor suppressor gene." (PMID 27031966, 2016). "Moreover, miR-21 has been associated with tumor cell invasion and metastasization in colorectal and breast cancers, where it targets tumor suppressor PDCD4 at a post-transcriptional level." (PMID 24672771, 2014). "PGE2 induces increase in miR-21 expression causing further downregulation of PDCD4 protein levels (and potentially other miR-21 targets) thus facilitating further progression of the tumour to more malignant stages and these effects can be reversed using miR-21 inhibitors (right side)." (PMID 25310697, 2014). "A confirmed target of miR-21, PDCD4 influences production of pro-inflammatory signaling through its interaction with AP-1, NF-κB, and eIF4A, and has been linked to the inflammatory microenvironment surrounding tumor cells." (PMID 24098127, 2013). "Moreover, erioflorin inhibited the tumor-associated activity of known Pdcd4- and IκBα-regulated αtranscription factors, that is, AP-1 and NF-κB, altered cell cycle progression and suppressed proliferation of various cancer cell lines." (PMID 23056346, 2012). "As a tumor suppressor protein, PDCD4 has been implicated in a number of cancers where it is often inhibited and/or downregulated, disrupting its ability to inhibit eIF4A translational and AP-1 transcriptional activity, processes that are important for cell growth and survival." (PMID 20661426, 2010). "PDCD4 was under-expressed in 43/50 (86%) OSCCs, with significantly reduced mRNA levels in patients with nodal metastasis (p = 0.0027), and marginally associated with T3-T4 tumor stage (p = 0.054)." (PMID 20831814, 2010). "In addition to its tumour suppressor properties, PDCD4 also has diagnostic and prognostic utility and represents a promising target for anti-cancer therapy." (PMID 20122155, 2010). "Furthermore, PDCD4 has several functions in cancer, and its dysregulation is associated with tumor growth and an increased risk of AF, so it may be a therapeutic target for both diseases." (PMID 40766329, 2025). "Additionally, emerging CAR T-cell therapies are being designed to overcome metabolic challenges in solid tumors by enhancing mitochondrial function and resistance to tumor microenvironment stressors, which aligns with the metabolic pathways linked to PDCD4 observed in our analysis." (PMID 40766329, 2025). "Moreover, to determine whether PDCD4 correlates with Gleason grade, whose higher grade indicates increased tumor aggressiveness and the likelihood of disease recurrence, we examined the association of PDCD4 expression and Gleason grade." (PMID 34525952, 2021).